CD4 (CD4 molecule)
Diseases named in the same sentence as CD4 in open-access papers (continued):
Sharing a sentence is not in itself a finding about the gene and the disease.
infection (continued). "However, baboon and rhesus macaque isolated CD4 cells are equally permissive to infection." (PMID 39006742, 2024). "However, neither CD4 T cells or B cells appear to be absolutely required for protection against secondary challenge since both CD4−/− and MuMT mice had reduced parasite levels during secondary infection compared to primary infection despite their inability to clear the primary infection." (PMID 38392861, 2024). "However, the subsequent step leading to productive infection of the macrophage target relies on interactions between the viral envelope and the CD4 receptor and the CCR5 coreceptor, as it is inhibited by antibodies or drugs targeting Env and CD4, and to a lesser extent by antagonists of CCR5." (PMID 38400063, 2024). "Interestingly, while CX3CR1 serves as a marker for these highly differentiated CD4+ T cells, its absence or deficiency did not impact the accumulation of CD4+ T cells in key organs such as the spleen, lung, or liver during the infection." (PMID 39061246, 2024). "Infection with the species Schistosoma mansoni (S. mansoni) results in hepatic and intestinal granulomatous inflammation around trapped parasite eggs, which is the result of the activation of an adaptive immune response mediated by CD4 T cells specific for egg antigens." (PMID 38559160, 2024). "The observed changes in CD8 + and CD4 + T cells may indicate an enhancement of immune system activity, while the decrease in CD19 + B cells was reported to be accompanied by reduced immunoglobulins and an increased risk of infection." (PMID 39026154, 2024). "It is possible that an impact of Zip/sZip and SIRT7 on HIV gene expression may be more apparent in contexts where HIV-1 Vpr enhances infection, such as spreading infection of myeloid lineage cells or carefully characterized and titrated infections in cycling CD4+ T-cells." (PMID 39205287, 2024). "In addition, 11.8% of patients presented an additional serious infection not directly associated with the drug, even with a mean CD4+ T cell count of 609 cells/μL." (PMID 39429408, 2024). "However, the phenotypic and resident characteristics of CD4+ Trm cells during infection remain unclear." (PMID 38779662, 2024). "Additionally, WLWHIV with baseline CD4 T-Cell counts below 200 showed the highest infection rates." (PMID 38778266, 2024). "Thus, we show substantial diversity in recall responses mounted by multiple co-existing CD4+ T cell subsets in the spleen, and present graphical user interfaces for studying gene expression dynamics and clonal relationships during re-infection." (PMID 38944658, 2024). "Unlike in controls, previous infection of patients was even associated with higher levels of spike-specific CD4+ T cells, which may reflect prolonged encounter with antigen during infection." (PMID 38326340, 2024). "CD4+ T cells that expressed the inhibitory protein Cytotoxic T-lymphocyte-associated protein 4 (CTLA-4) were decreased in individuals with Sh infection compared to persons without infection." (PMID 39250522, 2024). "Studies have indicated that animals that have been successfully immunized with a subunit or live attenuated B. bovis or are persistently infected and have survived the acute stage of infection may rely on CD4+ T cells that are specific to the antigen and produce interferon gamma (IFN-γ)." (PMID 37563668, 2023). "Thus, accumulating evidence suggests that antigen-specific Tr1 cells develop either soon after or in parallel with corresponding effector CD4+ T cell populations as a mechanism to control the extent and magnitude of these latter CD4+ T cell responses during infection." (PMID 37917177, 2023). "Furthermore, significant nonlinear association were observed between Bh infection risk and CD4+ T cell counts, HIV VL, as well as duration of treatment interruption." (PMID 37697423, 2023).
infection (continued). "Moreover, the lower VL in chronic infections than in recent infections might be due to the nature of the cohort where participants with a longer infection duration who still had a high CD4+ cell count are likely to better control the infection innately." (PMID 36595537, 2023). "Due to the acute infection caused by IAV in our study, we therefore speculated that the decreased CD4+ T cells in the co-infected group contributed to less IFNγ production, thereby leading to the diminished killing effects of CD8+ T cells against secondary T. gondii infections." (PMID 37235437, 2023). "Given that central memory CD4+ T cells represent an important subset that harbor latent provirus with the capacity to re-establish infections (91, –, 93, 127), their ability to recirculate through secondary lymphoid tissues may be instrumental to their long-term survival under ART." (PMID 37747190, 2023). "Altogether these data show that the viability of infected virus-donor CD4+ T cell dictates the mode of virus transmission toward macrophages, and that the heterotypic cell fusion mechanism, largely favored with living infected T lymphocytes, is by far the most effective mode of infection." (PMID 36988579, 2023). "Moreover, because of the ability of calnexin to induce the clonal expansion of calnexin-specific CD4+ T cells during infection, this vaccine may present an immunotherapeutic effect." (PMID 37367569, 2023). "Consequently, we further investigated CD4+ T cell differentiation in both infection groups." (PMID 37211685, 2023). "Serial assessment of CD4 Tvis against adenovirus, cytomegalovirus, and herpes symplex virus allowed personalized steering of immunosuppressive therapy with a net reduction of the exposure to unnecessary overimmunosuppression, reduced infection events, and comparable kidney function." (PMID 36648536, 2023). "Higher numbers of IFNγ-expressing CD4+ T cells and higher frequencies of proliferating (Ki-67+) CD4+ T cells were nonetheless observed after viral antigen stimulation in the SGs of Cd4Cre/+Arg1flox/flox versus Cd4+/+Arg1flox/flox mice during the chronic phase of infection with MCMV." (PMID 37440306, 2023). "We also compared the infection rates in IEC-stimulated T cells with those stimulated by Human Umbilical Cord Vascular Endothelial Cells (HUVEC) and Lymphatic endothelial cells (LEC), the two EC types associated with inducing HIV infection in resting CD4 + T cells shown previously." (PMID 37202790, 2023). "To examine whether IEC stimulation would activate resting CD4 + T cells, we measured cell activation markers CD25, CD69, and HLA-DR in IEC-stimulated resting CD4 + T cells on day 6 post-infection using fluorescently labeled antibodies against these markers and flow cytometry." (PMID 37202790, 2023). "Thus, single-dose immunized convalescent patients and two-dose infection-naïve vaccinees generate comparable frequencies of CD4+ T lymphocytes specific to the spike epitope S751-767, and a third booster vaccine dose did not further this frequency beyond the peak already achieved." (PMID 37388738, 2023). "Moreover, we observed a correlation between B cell MHCII expression and susceptibility to infection in CD19CreiABfl/fl mice treated with IgG, but not in CD19CreiABfl/fl mice depleted of CD4+ T cells." (PMID 37721965, 2023). "Therefore, the IL-10 production induced in CD4+ T cells by IgG from asymptomatic carriers may collaborate with a clinical control of the disease or infection control on patients submitted to therapeutic protocols." (PMID 37711742, 2023). "Our data showing reduced placental transmission and absence of fetal loss after non-primary as opposed to primary infection in CD4+ T lymphocyte-depleted dams indicates that preconception maternal CMV-specific CD8+ T lymphocyte and/or humoral immunity can protect against cCMV infection." (PMID 37796819, 2023).
infection (continued). "Secondly, we show that a homologous Ad26.COV2.S boost increased the magnitude of the antibody response to similar levels regardless of prior infection status, or the infecting variant, and expanded the proportion of early differentiated memory CD4 T cells specific for spike." (PMID 37943890, 2023). "Thus, it was of interest to determine if the increase in parasite burden and lag in parasite clearance observed in Bhlhe40−/− mice was due to elevated IL-10 production, particularly by CD4+ T cells, given their role in IL-10 production in response to this infection." (PMID 37843306, 2023). "It is possible that the numerically increased CD4+ population found 1mo p.i. in experiments reported here contained regulatory cells that prevented immune-related cognitive dysfunction at that time, but this positive effect waned as these cells returned to pre-infection levels by 4 mo p.i." (PMID 37143648, 2023). "Noteworthy, by day 10 post-infection, Tregs infiltrating the skin were now also significantly increased in this group, evidencing significant temporal and phenotypical dynamics of virus-specific CD4+ T cells infiltrating the infected skin in the different groups." (PMID 37371900, 2023). "In addition, after infection with T. gondii, CD4+ T cells and CD8+ T cells secrete inflammatory factors such as TNF-α and IL-1 to stimulate microglia, and interfere with gamma-aminobutyric acid (GABA) and 5-hydroxytryptamine (5-HT) synthesis via the KYNA pathway." (PMID 37077528, 2023). "A number of participants had missing CD4 cell counts, HIV-RNA, blood sample test and biochemistry measurements hindering a more accurate evaluation of laboratory results association with the infection by multidrug-resistant M. tuberculosis and unsuccessful treatment outcome." (PMID 36952578, 2023). "The outcome and special contributions of MHC-I molecule H-2Db, the early anti-viral CD8+T cell response to a TMEV-infection, the reaction of CD4+ T helper and effector cells as well as regulatory T cells (Tregs) could not be differentiated in the present study, utilizing a generalized CD28-knockout." (PMID 37090733, 2023). "To determine whether an unusually rapid disease progression in B6.I-103 mice was accompanied by shifts in the lung tissue infiltration, we compared the lungs of B6, B6.I-9.3 and B6.I-103 mice with respect to the influx of CD4+ T-lymphocytes at the early phase of infection (week 3 post challenge)." (PMID 37426653, 2023). "However, CD4+ (T-helper cells) remains higher after infection." (PMID 36909038, 2023). "Infection with Pg induces the expansion of both total and subpopulations of MDSCs in the bone marrow and spleen among 8-week-old wild-type mice, of which only mMDSCs could strongly suppress the proliferation of CD4+ T cells." (PMID 36864466, 2023). "The observation that Bhlhe40−/− CD4+ T cells exhibit a significant increase in IL-10 RNA and protein production suggests that Bhlhe40 acts during the early stages of a P. yoelii infection, to suppress IL-10 expression in CD4+ T cells, as it does in response to other Th1-centric infections." (PMID 37843306, 2023). "In this model, we observed 100% vertical transmission and 83% fetal loss in CD4+ T lymphocyte-depleted CMV-seronegative macaques infected with RhCMV in late first / early second trimester gestation, with protection conferred by passive infusion of high potency anti-CMV antibodies prior to infection." (PMID 37796819, 2023). "In summary, Sap2‐273L infected mice displayed higher fungal load overall, less C3a release all the time, more exhausted CD4+ T cells, Treg cells and M2 macrophage induced, as well as less pro‐inflammatory cytokines released, but more IL‐10 and IL‐9 production at day 12 post‐infection." (PMID 37211685, 2023).
infection (continued). "Infection with HIV in humans or with SIV in macaques leads to damage of the mucosal barrier of the gastrointestinal tract, causing an increased translocation of microbial products and a significant decrease in activated memory mucosal CD4+ T cells at this anatomical site." (PMID 37764928, 2023). "The preponderance of central memory CD4+ T cells (clusters 0 and 1) in infected individuals compared to vaccinated individuals was accentuated in antigen-specific cells from the acute time point post-infection where we discovered even higher proportions of central memory cells." (PMID 37790414, 2023). "In contrast with CD8+ T cells, CD4+ T cells show a primarily central memory effector (CCR7+ CD45RA−) phenotype eight months after infection which, with self-renewing capacity, indicates that SARS-CoV-2 specific T cell memory after infection might be long lasting and maintained for many years." (PMID 38027416, 2023). "Our findings support the concept that effector memory CD4+T cells could persist in circulating blood following infection, poised to perform functional roles upon re-stimulation, including Th1 cytokine responses and provision of B cell help for antibody production." (PMID 37173361, 2023). "Interestingly, infection with C. felis at week 9 (0 dpi) resulted in drastic changes in the B- and T-cell populations, and an inversion in both the B-cell:T-cell ratio and the CD4+:CD8+ cells was observed following C. felis challenge." (PMID 36992157, 2023). "Furthermore, it remains unclear how well circulating rotavirus VP6-specific CD4+ T cell responses represent at the site of infection and how they are directly involved in anti-viral clearance." (PMID 37268634, 2023). "Also, the frequency of S-specific CD4+ T cell response is influenced by previous natural infection." (PMID 37575243, 2023). "In this regard, increasing CD4+ and CD8+ CE-XTC frequencies in both blood and tissues, protecting the CD4+ NHP CE-XTC against infection, and/or enhancing their virus-specific function could tip the balance towards stable control of viremia in the absence of suppressive ART." (PMID 37207227, 2023). "Additionally, ⍺4β7high CD4+ memory T cells collected from HIV infected subjects in the early stages of infection (FIEBIG II/III) are enriched in HIV proviral DNA, relative to other CD4+ T cell subsets, and this same subset is selectively infected and depleted from SIV infected macaques." (PMID 38064524, 2023). "Follow-up studies from patients who recovered from the closely related coronavirus SARS-CoV-1 outbreak revealed that virus-specific humoral responses significantly decline 1 year post-infection while long-lasting memory CD4 and CD8 T cells could be detected as long as 11 years after infection." (PMID 37404819, 2023). "Further, although the composition of the DC subset changed during infection, the magnitude of the T cell response to soluble protein immunization was similar in both uninfected and infected mice, indicating that DCs were competent to activate CD4+ T cells in a Plasmodium-infected spleen." (PMID 36715223, 2023). "Significant nonlinear associations were observed between the Bh infection risk and CD4+ T cell counts (Pfor nonlinearity < 0.001, L-shaped), HIV VL (Pfor nonlinearity < 0.001, inverted U-shaped), and duration of interruption in HARRT (Pfor nonlinearity < 0.001, inverted U-shaped)." (PMID 37697423, 2023). "Another study found that global absence of Fut8 impaired CD4+ T cell-B cell interactions without affecting the interaction between CD4+ T cells and dendritic cells, which was associated with diminished humoral responses following infection with Salmonella typhimurium." (PMID 38027254, 2023). "In addition, BBV152/Covaxin generated a robust CD4+ T-cell response in most individuals (85%), which was stable for 6 months and included cells capable of recognizing spike and nucleoprotein with a frequency comparable to infection." (PMID 37388738, 2023).
infection (continued). "This strategy has the advantage for this study of including animals with perturbations to their humoral responses, as CD4+ T cell depletion results in a delay in humoral responses and passive antibody infusion introduces a high titer of RhCMV-specific antibodies prior to infection." (PMID 37131785, 2023). "Reactivation of a latent JCPyV infection and its development into PML generally requires the immune system to be compromised—the severity of such a state can be measured with several diagnostic methods, CD4 lymphocyte count being the most common in HIV-positive patients." (PMID 36774452, 2023). "This principle also predicts that HIV-productive infections should track the site and availability of target cells that accompany an evolving and continuing immune response, which will increase the frequency of CD4+ T cells and T follicular helper (Tfh) cells in B cell follicles." (PMID 37733443, 2023). "Adoptive transfer of CD4+ and CD8+ T cells alone to infected SCID mice was sufficient to eliminate infection, conversely wild-type (WT) mice depleted of both T cells were susceptible to infection, whereas depletion of only one type of T cell, controlled infection." (PMID 37679410, 2023). "Since infection and inflammation drive commensal-specific CD4+ T cells toward Th1 and Th17 differentiation, these data suggest that the Th1/Th17 axis, rather than a Th2 response, could drive inflammation in the intestinal mucosa of EGPA patients with GI manifestations." (PMID 35740247, 2022). "Therefore, the mechanism of CTL CD4 response is essential to utterly understand the process of DENV and ZIKV elimination in order to produce effective and reliable vaccines against these multiple co-circulating infections caused by related Flavivirus." (PMID 36159640, 2022). "The cell types showing the highest frequency of F-MuLV and SFFV infection in the late phase were erythroblasts, B cells and myeloid cells in the bone marrow, erythroblasts and B cells in the spleens, and erythroblasts, B cells and CD4+ T cells in the lymph nodes." (PMID 36527061, 2022). "This reactivity to H. pylori ferritin, likely due to previous infection with Helicobacter, supports the hypothesis that a subset of human donors has H. pylori ferritin-specific CD4 T cells that have the potential to be recalled in response to immunization with ferritin-based vaccine constructs." (PMID 36289232, 2022). "However, resting CD4+ T cells poorly support productive infection." (PMID 35062339, 2022). "Increasing expression of ICOS and CXCR5 on CD4+ T cells has also been reported, and circulating Tfh numbers increase for the duration of infection, thus, the increase in ICOS and CXCR5 may be attributed to the enhanced differentiation of Tfh, and increased glycolysis." (PMID 35493515, 2022). "Thus, we speculated that a lower percentage of CD4+ T cells in the early infection might contribute to decreased B-cell proliferation and eventually the fatal prognosis in JE patients." (PMID 35463639, 2022). "However, neutrophil, monocyte, infection biomarkers, individual lymphocyte subset counts (total T lymphocyte, CD4+ T cell, CD8+ T cell, B cell, and NK cell counts), and lymphocyte subset functions were similar in bacterial sepsis patients and SARS-CoV-2 sepsis patients." (PMID 36032159, 2022). "Increased HTLV-1 transmission may occur in individuals infected with other sexually transmitted diseases because these infections induce inflammatory reactions that recruit lymphocytes, which have a high proportion of CD4+ T-cells facilitating HTLV-1 transmission." (PMID 36298639, 2022). "Moreover, in Hodgkin’s lymphoma, genetic analysis determined that CXCR5+ ICOS+ CD8+ T cells are most closely related to CD4-derived Tfh than other cell populations, and thus these cells may undergo similar metabolic alterations under conditions of infection." (PMID 35493515, 2022).